GSTM1 (glutathione S-transferase mu 1)
Diseases named in the same sentence as GSTM1 in open-access papers (continued):
Sharing a sentence is not in itself a finding about the gene and the disease.
lung carcinoma (continued). "The genotype combination of GSTM1 (null)/GSTT1 (null) and GSTT1 (null)/GSTP1 (Ile/Ile) showed increased susceptibility towards lung cancer." (PMID 31554367, 2019). "The ‘at risk’ genotype combination GSTM1 (null) /GSTT1 (null) (OR=1.76, 95%CI; 0.920-3.370, p-value=0.03) showed increased susceptibility to lung cancer risk." (PMID 31554367, 2019). "GSTM1 deletion is known to be protective for lung cancer among individuals with a high intake of cruciferous vegetable and deleterious among those with low intake of cruciferous vegetable." (PMID 31555322, 2019). "Genotype combination of GSTM1 (null)/GSTT1 (null) and GSTT1 (null)/GSTP1 (Ile/Ile) considered to be ‘at risk’ genotypes showed strong association towards risk of lung cancer in north Indian population." (PMID 31554367, 2019). "GSTM1 (null)/GSTP1 (Ile/Ile) (OR=1.174, 95%CI=0.704-1.957), GSTT1 (null)/GSTP1 (Ile/Val+Val/Val) (OR=1.354, 95%CI=0.778-2.356) correlated to lung cancer risk and statistically non- significant." (PMID 31554367, 2019). "Gene-gene interaction for null genotypes of GSTM1 and GSTT1 were correlated with higher risk of having lung cancer." (PMID 31554367, 2019). "To date, some previous meta-analyses have only studied the association between GSTM1 and/or GSTT1 alone gene polymorphisms and risk of lung cancer." (PMID 28427236, 2017). "Second, This is the first meta-analysis to explore the combined GSTM1 and GSTT1 effects and lung cancer risk." (PMID 28427236, 2017). "Significant association was found between the combined effects of GSTM1 and GSTT1 polymorphisms and lung cancer risk when all the eligible studies were pooled into the meta-analysis." (PMID 28427236, 2017). "In summary, this meta-analysis indicates that the combined effects of the GSTM1 and GSTT1 polymorphisms are associated with increased lung cancer risk in Asians, Caucasians, and Indians." (PMID 28427236, 2017). "CYP1A1-rs1048943 GG+AG genotype, GSTM1 deletion genotype, mEH-rs1051740 mutant genotype, XRCC1-rs1799782 TT+CT genotype, XRCC1- rs25489 GG genotype showed significant correlations with lung cancer risk increased." (PMID 29212267, 2017). "The lung cancer patients bearing the favorable GSTM1 null genotype were more likely to have better response rates to platinum-based chemotherapy compared to those with the unfavorable GSTM1 present genotype, especially in Asian patients." (PMID 28572675, 2017). "To date, a series of previous meta-analysis have only focused on the association between single GSTM1 or GSTT1 gene polymorphism and lung cancer risk." (PMID 28427236, 2017). "In summary, this meta-analysis indicates that the combined effects of GSTM1 and GSTT1 polymorphisms is associated with increased lung cancer risk in Asians, Caucasians, and Indians." (PMID 28427236, 2017). "Significant association was observed between the combined effects of GSTM1 and GSTT1 polymorphisms and lung cancer risk when all the eligible studies were pooled into the meta-analysis." (PMID 28427236, 2017). "Another group from North India demonstrated that the risk of lung cancer is associated with CYP1B1 and GSTM1 polymorphisms in the population." (PMID 27090234, 2016). "Among the variety of xenobiotic metabolising enzymes, CYP1A1, GSTM1 and GSTT1 have been implicated to modulate the risk of lung cancer because of their potential involvement in carcinogenesis metabolism." (PMID 27090234, 2016). "In the current study, GSTM1 wild and null genotypes were detected, respectively, in 73.98 and 26.1 % of lung cancer patients." (PMID 27090234, 2016). "In an Indian population study, a twofold risk of lung cancer was found in individuals displaying variations in the CYP1A1 and GSTM1 genes." (PMID 27090234, 2016). "In our study, the combinations of two (CYP1A1 m2 and GSTM1) or three (CYP1A1 m1, CYP1A1 m2 and GSTM1/GSTT1) genotypes had a profound effect on susceptibility to lung cancer up to 14-fold depending on the genotypic interaction." (PMID 27090234, 2016).
lung carcinoma (continued). "On the contrary, GSTM1 null or deletion genotype was reported to be prevalent in about 50 % of Caucasians, 33 % of African Americans and 45 % of Japanese lung cancer patients." (PMID 27090234, 2016). "CYP1A1, GSTM1, GSTP1 and GSTT1 polymorphisms and their association to lung cancer in a cohort of North Indian population was reported." (PMID 27090234, 2016). "The GSTM1-null genotype, the AKR1C3 (Ex1-70C > G), OGG1 (Ex6-315C > G) genotypes were closely associated with increased risk of lung cancer in Xuanwei County, and their odds ratios (95%CI) were 2.3 (1.3-4.2), 1.8 (1.0-3.5) and 1.9 (1.1-3.3), respectively." (PMID 25603868, 2015). "Taken together, after a decade of extensive studying on this topic, our findings suggest that GSTM1 and GSTT1 genetic polymorphisms are associated with increased lung cancer risk in the Chinese population." (PMID 25036724, 2014). "We ultimately identified a total of 71 articles reporting the relationship between GSTM1 and/or GSTT1 genetic polymorphisms and lung cancer risk from both Chinese and English databases." (PMID 25036724, 2014). "We evaluated the main effects of phase I/phase II xenobiotic metabolism genes (CYP1A1, GSTM1, GSTP1 and GSTT1) in relation to lung cancer susceptibility using univariate as well as multivariate statistics." (PMID 23013535, 2012). "We evaluated the impact of polymorphisms detected in 4 in Phase I and Phase II metabolism genes (CYP1A1 MspI T6235C, GSTM1 present/null, GSTT1 present/null and GSTP1 Ile105Val) on the risk of developing lung cancer." (PMID 23013535, 2012). "The study examined the relationship between polymorphisms in CYP1A1 and GSTM1 and aberrant methylation of p16, DAPK and RARβ in lung cancer." (PMID 20704749, 2010). "One of the first meta-analyses showed a modest increase in lung cancer among carriers of the GSTM1-null genotype (OR = 1.13, 95%CI 1.04-1.25)." (PMID 20704749, 2010). "The findings suggest that smoking related biological pathways leading to the development of lung cancer involve not only hypermethylations of p16, DAPK and RARβ promoters but also genetic polymorphisms of CYP1A1 and GSTM1 genes." (PMID 20704749, 2010). "The prevalence of GSTM1-null genotype in the lung cancer patients was 49%, compared to 52.6% in the control group (OR = 1.39, 95% CI = 0.70–1.90, p = 0.57)." (PMID 17897446, 2007). "For instance, individuals lacking GSTM1, an enzyme involved in ROS detoxification, exhibited greater lung cancer risk when exposed to elevated levels of residential radon or secondhand smoke, supporting a gene–environment interaction via oxidative pathways." (PMID 40823246, 2025). "Hence, the present study was designated to investigate the possible correlations of GSTM1 and GSTT1 polymorphisms with lung cancer susceptibility." (PMID 39619061, 2024). "Moreover, subgroup analysis showed that cancer risks in GSTM1-null was organ-specific, especially for lung cancer and nasopharyngeal cancer among smokers, and liver cancer, head and neck cancer and stomach cancer among drinkers." (PMID 38579033, 2024). "However, only a few studies have been conducted in the Bangladeshi population demonstrating the association of GST (GSTM1 and GSTT1) polymorphisms with the risk of lung cancer having a small sample size." (PMID 39619061, 2024). "No statistically significant increased risk of lung cancer was found in both smokers and nonsmokers based on GSTM1 and GSTT1 genotypes." (PMID 39619061, 2024). "It has been reported that glutathione metabolism in brain metastases from NSCLC is regulated by glutathione peroxidase and glutathione S-transferase; among them, GPX4 and GSTM1 are overexpressed in BM subsets, and cause massive consumption of GSH in brain metastases of lung cancer." (PMID 36589232, 2022).
lung carcinoma (continued). "Thirty-five previous meta-analyses have been reported on the individual glutathione S-transferase M1 (GSTM1) present/null, glutathione S-transferase T1 (GSTT1) present/null, and glutathione S-transferase P1 (GSTP1) IIe105Val polymorphisms with lung cancer (LC) risk." (PMID 34190143, 2021). "Although early research suggested a weak association exists between certain GST gene mutations (e.g., GSTM1, GSTM3, GSTP1, and GSTT1) and risk of lung cancer, more recent work has not evidenced any definitive links between GSTM3 polymorphisms and lung cancer risk." (PMID 33568630, 2021). "There are reports that GSTM1 has no relevant modifying effect on lung cancer risk and cumulative smoking dose." (PMID 32030321, 2020). "Genotype combinations of GSTM1 (positive) /GSTT1 (null) (OR=1.5, 95% CI=0.887-2.5360) and GSTM1 (null)/GSTT1 (positive) (OR=1.174, 95%CI=0.670-2.057) were associated with lung cancer risk but statistically non significant." (PMID 31554367, 2019). "GSTM1 or GSTT1 gene polymorphism and amino acid changes in GSTP1 have been correlated and may be associated to lung cancer risk." (PMID 31554367, 2019). "Therefore, we performed a meta-analysis to investigate the combined effects of GSTM1 and GSTT1 and lung cancer risk." (PMID 28427236, 2017). "GSTM1 and GSTT1 null genotype lost enzymatic functional activity, therefore, may increase the risk of lung cancer." (PMID 28427236, 2017). "Therefore, we performed a meta-analysis to investigate the combined effects of GSTM1 and GSTT1 polymorphisms and lung cancer risk." (PMID 28427236, 2017). "The impact of CYP1A1 m1, CYP1A1m2, GSTM1 and GSTT1 gene polymorphisms on superoxide dismutase activity, Glutathione peroxidase activity, MDA and 8-OHdG levels were assessed between controls and lung cancer patients." (PMID 27090234, 2016). "Correlations between lung cancer risk and combinations of CYP1A1, GSTM1 and GSTT1 is of particular interest since these genotypes suggest that alterations in the action of phases I and II enzymes lead to defective metabolism of xenobiotic compounds, thereby potentiating the cancer risk." (PMID 27090234, 2016). "Results of our study and others indicate that in the Indian context, the risk of lung cancer is more associated with GSTT1 polymorphism rather than GSTM1 genotype." (PMID 27090234, 2016). "CYP1A1, GSTM1 and GSTT1 polymorphisms and the association with lung cancer in the South Indian population (patients reporting to a specific hospital in Thiruvananthapuram, the capital city of Kerala state) was reported, suggesting the risk in the specific population of that state." (PMID 27090234, 2016). "Results of our study indicate that CYP1A1 polymorphisms rather than GSTM1 polymorphisms and smoking contribute to the higher risk of lung cancer." (PMID 27090234, 2016). "In the present study, no risk of lung cancer was associated with GSTM1 null genotype in smokers and non-smokers." (PMID 27090234, 2016). "After being stratified by smoking status, the GSTM1 null genotype was associated with an increased risk of lung cancer in both smokers and nonsmokers." (PMID 25797617, 2015). "The interaction of CYP1A1 (Msp1) with mt/mt genotype and GSTM1 null genotype could enhance the risk of lung cancer, and the OR of which were a little higher than the other two CYP1A1 (Msp1) genotypes with GSTM1 null." (PMID 25036724, 2014). "For instance, under a higher OR with no heterogeneity, people with CYP1A1 (mt/mt) and GSTM1 null genotype should pay more attention to avoiding exposure to harmful environmental factors associated with lung cancer." (PMID 25036724, 2014). "Our pooled analysis on the original studies in the Chinese population provided efficient and effective evidences of an increased association between null GSTM1, null GSTT1 or dual null GSTM1-GSTT1 genotypes and lung cancer risk when omitting some possible heterogeneous records." (PMID 25036724, 2014).
lung carcinoma (continued). "No significant increase in the risk of lung cancer was detected in either null genotype of GSTM1 in the northwest, or null genotype of GSTT1 in the north, southwest or northwest of China." (PMID 25036724, 2014). "Besides, individuals with GSTM1 and GSTT1 null genotypes were reported better protected from lung cancer than those with GSTM1/GSTT1 positive genotypes when exposing to cruciferous rich diets." (PMID 25420021, 2014). "The excess lung cancer risk was found associated with null GSTM1 genotype, but not with null GSTT1 genotype, in both smokers and nonsmokers." (PMID 25036724, 2014). "When we analyzed the association between the GSTM1 genotypes and lung cancer risk, we found that the ≥1 null allele was no associated with the risk of developing lung cancer (adjusted OR = 0.95; 95% CI = 0.76-1.19)." (PMID 23013535, 2012). "We investigated if the individual and/or combined modifying effects of the CYP1A1 MspI T6235C, GSTM1 present/null, GSTT1 present/null and GSTP1 Ile105Val polymorphisms are related to the risk of developing lung cancer in relation to tobacco consumption and occupation in Asturias, Northern Spain." (PMID 23013535, 2012). "In 2006, one meta-analysis of 130 studies (over 23,000 cases and 30,000 controls) reported the weakly positive, but not significant association between the GSTM1 null genotype and the risk of lung cancer." (PMID 24212786, 2011). "Smokers with the GSTM1 enzyme have approximately one-third of the risk for lung carcinoma than smokers without the enzyme." (PMID 22206016, 2011). "Carlsten had reported the similar phenomenon for GSTM1 polymorphism which conferred a significantly increased risk of lung cancer to East Asians but not to Caucasians." (PMID 20663177, 2010). "In addition, only a relative small study has examined the relationship between polymorphisms in XRCC1, GSTM1, GSTP1, NQO1, and MPO and aberrant methylation of p16, RARβ and MGMT in lung cancer." (PMID 20704749, 2010). "In conclusion, we observed that carrying the GSTM1 genotype is not a risk factor for lung cancer, alone." (PMID 17897446, 2007). "Some studies suggest that the GSTM1 null genotype confers an increased risk of lung cancer but this result has not been approved by others, especially recent meta and pooled analysis." (PMID 17897446, 2007). "However, β-carotene supplementation does not modify the correlation between GSTM1 and the risk of lung cancer development." (PMID 36793931, 2023). "However, at any case, the association between the combined effects of GSTM1 and GSTT1 polymorphisms and lung cancer risk in Indians essentially remains an open field, as the number of studies (n = 3) is considerably smaller than that needed for the achievement of robust conclusions." (PMID 28427236, 2017). "However, high heterogeneities in the analysis of the association between GSTM1 variants and lung cancer were found in the studies from northeast and southwest China." (PMID 25036724, 2014). "Data on genetic polymorphisms of glutathione S-transferase Mu 1 (GSTM1) from 68 studies, glutathione S-transferase theta 1 (GSTT1) from 17 studies and GSTM1-GSTT1 from 8 studies in the Chinese population were reanalyzed on their association with lung cancer risk." (PMID 25036724, 2014). "Besides, smokers had a higher risk than non-smokers in the association between GSTM1 null genotype and lung cancer risk." (PMID 25036724, 2014). "The aims of the present study are to evaluate the frequencies of GSTM1 gene polymorphisms in Turkish population and whether genetic polymorphisms in GSTM1 influence individual susceptibility to lung cancer in Turkish population or not." (PMID 17897446, 2007). "We have observed that GSTM1 genotype is not an independent risk factor for lung cancer." (PMID 17897446, 2007). "The null genotype for both GSTM1 and GSTT1 with estimated odd ratio (OR=1.76, 95% CI: 1.030-3.012, p=0.03) found to be statistically significant in lung cancer patients." (PMID 31554367, 2019).
lung carcinoma (continued). "In smokers having lung cancer both GSTT1 (80.35%) and GSTM1 (73.21%) null genotypes were higher than controls of GSTT1 (46.15%) and GSTM1 (57.69%)." (PMID 31554367, 2019). "Therefore, genetic polymorphisms of CYP1A1-rs1048943, GSTM1, GSTT1, mEH-rs1051740 and XRCC1(rs1799782, rs25489), methylation of p16 and RASSF1A gene, and telomere length were analyzed in peripheral blood both from lung cancer patients and health controls to explore their correlation." (PMID 29212267, 2017). "The relationships of GSTM1 and GSTT1 genotypes and the survival rates in lung cancer are revealed to be quite conflicting also." (PMID 28572675, 2017). "Additionally, smokers with GSTM1 null genotype had a higher lung cancer risk than non-smokers." (PMID 25036724, 2014). "Among the members of the GST superfamily, GSTM1, GSTT1 and GSTP1 genotypes are considered to be the most related to the development of many cancers because their roles in lung cancer, acute leukemia and breast cancer have been identified in previous studies." (PMID 23717494, 2013). "The modification of the SHS effect by GSTM1 is consistent with previous studies on the association between SHS, GST polymorphisms, and lung cancer in never smokers and may reflect the additional impact of GSTM1 on liver metabolism of tobacco-derived electrophils." (PMID 19057702, 2008). "In the smoker's case, the frequency of the GSTM1 null genotype was nonsignificantly higher in lung cancer patients than in control (OR = 1.89, 95%CI = 0.96–3.71, p = 0.074)." (PMID 39619061, 2024). "Moreover, in lung cancer patients, 8.33% carried both GSTM1 and GSTT1 null genotype, and 56.11% had GSTM1 and GSTT1 positive." (PMID 39619061, 2024). "Radically altered profiles of BM metabolism and protein expression compared with primary lung cancer cells were described and GPX4 and GSTM1 were identified as being responsible for the high consumption of GSH, leading to decreased chemosensitivity by negatively regulating ferroptosis." (PMID 34586745, 2021). "But there are also reports the GSTM1 genotype both alone and in combination with the GSTP1 genotype alters the risk of developing lung cancer among nonsmokers." (PMID 32030321, 2020). "The results of the analysis of gene-gene interactions of CYP1A1 MspI T6235C, GSTM1 present/null, GSTT1 present/null and GSTP1 Ile105Val polymorphisms in lung cancer risk indicate that these genes do not interact in lung cancer development." (PMID 23013535, 2012). "Currently, however, the risk of lung cancer due to the CYP1A1 and GSTM1 genes has no clear evidence." (PMID 21859547, 2011). "Our meta-analysis suggests that the lung cancer patients bearing the favorable GSTM1 null genotype were more likely to have better response rates to platinum-based chemotherapy compared to those with the unfavorable GSTM1 present genotype in Asian patients, but not in Caucasian patients." (PMID 28572675, 2017). "Few antimalarial drugs such as Quinine, Quinidine have been reported to exhibit inhibitory effect on GSTM1, GSTP1; however, none of them has been reported to inhibit GSTA1 specifically, which has been found overexpressed specially in lung cancer." (PMID 32405336, 2020).